S100A10 (S100 calcium binding protein A10)
Diseases named in the same sentence as S100A10 in open-access papers (continued):
Sharing a sentence is not in itself a finding about the gene and the disease.
ovarian carcinoma (continued). "To date, there have been only three studies that have investigated the expression of S100A10 in ovarian cancer." (PMID 30572596, 2018). "Our preliminary studies investigating the mechanisms of chemotherapy resistance in ovarian cancer have shown increased S100A10 expression in chemotherapy-resistant disease compared to expression observed in the same patient tissue at diagnosis." (PMID 30572596, 2018). "Although many studies have investigated the functional role of annexin A2 in cancer cells, including ovarian cancer, S100A10 has been less studied." (PMID 30572596, 2018). "This article reviews the current understanding of S100A10 function in cancer with a particular focus on ovarian cancer." (PMID 30572596, 2018). "Future studies are required to investigate further the functional role of S100A10 in ovarian cancer, its usefulness in predicting chemotherapy response, and as a therapeutic target to overcome chemoresistance." (PMID 30572596, 2018). "Thus, S100A10 has enormous potential as a marker for predicting response to chemotherapy in ovarian cancer." (PMID 34944416, 2021). "In conclusion, the present study provides evidence of a definitive role for S100A10 in the progression of ovarian cancer, and its expression levels may affect cell sensitivity to carboplatin." (PMID 31739800, 2019). "Downregulation of S100A10 expression could inhibit cell proliferation and enhance ovarian cancer cell sensitivity to carboplatin, possibly involving the regulation of cleaved-Caspase3 and cleaved-PARP." (PMID 31739800, 2019). "Using Western blot assays, we also explored the possible mechanisms of S100A10 in ovarian cancer." (PMID 31739800, 2019). "Functional analyses demonstrated that S100A10 suppression significantly suppressed ovarian cancer cell proliferation, colony formation, cell migration and invasion, remarkably increased carboplatin-induced apoptosis in SKOV3 and A2780 cells and inhibited tumor growth in vivo." (PMID 31739800, 2019). "Nevertheless, the association of S100A10 with clinicopathological characteristics in ovarian cancer and its biological functions have not yet been clarified." (PMID 31739800, 2019). "S100A10 was mainly localized in the cytoplasmic compartment of ovarian cancer cells." (PMID 31739800, 2019). "Furthermore, we found that the level of S100A10 upregulation was significantly higher in carboplatin-resistant ovarian cancer." (PMID 31739800, 2019). "Our study is one of the most comprehensive studies of the expression of S100A10 in ovarian cancer." (PMID 31739800, 2019). "Furthermore, we performed a series of functional assays to determine the role of S100A10 in tumor progression and chemosensitivity of ovarian cancer cells in vitro." (PMID 31739800, 2019). "Thus, further studies are required to fully elucidate the molecular mechanisms through which S100A10 acts as a potential biomarker of the response to carboplatin in ovarian cancer." (PMID 31739800, 2019). "In addition, the mechanism of S100A10 in regulating carboplatin sensitivity in ovarian cancer was investigated." (PMID 31739800, 2019). "We examined the expression levels in tissues of S100A10 in 138 cases of ovarian cancer by IHC." (PMID 31739800, 2019). "A greater understanding of the functional role of S100A10 in ovarian cancer cells could lead to the development of effective strategies to target S100A10 and annexin A2, inhibit progression, and overcome chemotherapy resistance in ovarian cancer patients." (PMID 30572596, 2018). "The aims of this review are to highlight the current understanding of S100A10 function in cancer cells—with a particular focus on ovarian cancer—and to discuss the potential for using S100A10 as a predictive marker and targeting S100A10 to inhibit cancer progression and treatment resistance." (PMID 30572596, 2018).
ovarian carcinoma (continued). "Other studies have linked S100A10 with multidrug resistance in ovarian cancer; however, no functional studies to date have been performed in ovarian cancer cells." (PMID 30572596, 2018). "However, the functional role of S100A10 in the progression and carboplatin sensitivity of ovarian cancer is currently unknown." (PMID 31739800, 2019). "S100A10 knockdown significantly increased the apoptosis rate in SKOV3 and A2780 cells after 24 h of carboplatin treatment, demonstrating that S100A10 promotes carboplatin resistance in ovarian cancer cells." (PMID 31739800, 2019). "While the effects of ATRA on ovarian cancer proliferation and apoptosis have been previously investigated, to date no data has been reported on the effects of ATRA on both annexin A2 and S100A10 expression in serous ovarian cancer cells." (PMID 30621740, 2019). "Here, our research also supported that the high level of S100A10 may indicated reduced OS in serous, grade III, or stage III + IV ovarian cancer patients." (PMID 30558666, 2018). "The role of S100A10 in ovarian cancer has not been well studied and the effect of S100A10 on chemotherapy remains unclear." (PMID 31739800, 2019). "Additionally, in the present study, high expression levels of S100A10 predicted reduced PFS but not OS of ovarian cancer patients." (PMID 31739800, 2019). "Response to ATRA treatment in the ovarian cancer cell lines did not correlate with expression of ANXA2, S100A10 or retinoic acid receptor alpha (RARA) as all cell lines exhibited similar gene expression levels." (PMID 30621740, 2019). "Although is not clear why ovarian cancer cell lines are resistant to ATRA treatment, our study suggests that resistance to ATRA treatment is not dependent on RARA, ANXA2 or S100A10 expression as all of the serous ovarian cancer cell lines expressed similar mRNA levels of these genes." (PMID 30621740, 2019).
pancreatic cancer (15 papers, 2016 to 2023). "Low expression of S100A10 was associated significantly with better survival in pancreatic cancer by univariate analysis (P < 0.05)." (PMID 34530774, 2021). "Overexpression of S100A10 is also associated with poor prognosis in lung carcinoma and pancreatic cancer." (PMID 30572596, 2018). "(2003) identified the gene encoding the plasminogen receptor S100A10 as one of the upregulated genes in pancreatic tumors and cell lines compared to their normal counterparts." (PMID 30009399, 2018). "Depletion of S100A10 in pancreatic cancer cell lines resulted in decreased cell surface plasminogen activation and an overall reduction in cell invasiveness and tumor growth." (PMID 37892132, 2023). "S100A10 is upregulated in pancreatic cancer and contributes to cell proliferation, migration, invasion, and tumor growth." (PMID 37627239, 2023). "Many studies have shown that S100A10 is involved in the occurrence and development of ovarian, lung, colorectal and pancreatic cancers." (PMID 37420211, 2023). "For S100A10, our observations agree with the current literature describing the role of this S100 in promoting the development of pancreatic tumors." (PMID 37627239, 2023). "Sitek utilized mass spectrometry to identify 31 proteins (including S100A10) upregulated in pancreatic tumors." (PMID 34944416, 2021). "Consistent with previous studies, these results suggest a role of S100A10 in late events of pancreatic cancer." (PMID 34944416, 2021). "In our study, both bioinformatics analysis and experimental verification indicated that S100A10 was up-regulated in pancreatic cancer (vs normal controls/paraneoplastic tissue)." (PMID 34530774, 2021). "In summary, this study showed that both S100A10 mRNA and protein expression is significantly different in pancreatic tumors compared to normal tissue." (PMID 34944416, 2021). "In our study, we found that the mRNA level of S100A10 was highly expressed in pancreatic cancer and was related to the high tumor stage." (PMID 34804125, 2021). "According to Segara’s dataset, S100A10/A11 were also found higher expressed in pancreatic carcinoma (fold change = 4.3 and 7.52)." (PMID 34804125, 2021). "To gain further insight into S100A10 expression in pancreatic tumors beyond mRNA levels, we examined protein expression in 89 archived human pancreatic tumors using immunohistochemistry (IHC)." (PMID 30009399, 2018). "S100A10 was found to be highly overexpressed in pancreatic tumors, regulated the fundamental process of cellular invasion, regulated by KRAS signaling and DNA methylation, and contributed to tumor growth." (PMID 30009399, 2018). "(2009) who utilized mass spectrometry to identify 31 proteins (includes S100A10) that were overexpressed in pancreatic tumors." (PMID 30009399, 2018). "We analyzed these studies and demonstrated that S100A10 mRNA is highly expressed in pancreatic tumors and cell lines." (PMID 30009399, 2018). "Considering the role of S100A10 in pancreatic cancer cell invasion in vitro, we addressed the role of S100A10 during in vivo tumorigenesis." (PMID 30009399, 2018). "This presents the possibility that S100A10 upregulation by pancreatic tumors is a late event that appears to be unique to PDAC." (PMID 30009399, 2018). "A more recent study found that knockdown of S100A10 inhibits the growth of pancreatic cancer cells PANC-1 in immunocompromised NOD/SCID mice." (PMID 30572596, 2018). "Here, we introduce the plasminogen receptor S100A10 as a novel predictive biomarker and a driver of pancreatic tumor growth and invasion." (PMID 30009399, 2018). "We demonstrated that the expression of the plasminogen receptor S100A10 was driven by oncogenic KRASG12D which contributed to the enhancement of plasmin generation by pancreatic cancer cells." (PMID 30009399, 2018). "A consistent upregulation of S100A10 mRNA was observed in pancreatic tumors compared to normal tissues of unmatched and matched patients." (PMID 30009399, 2018).
pancreatic cancer (continued). "After establishing that S100A10 mRNA was highly expressed in pancreatic tumors and cell lines, we focused on studying its relevance in this cancer." (PMID 30009399, 2018). "Using the pancreatic cancer cells isolated from iKRas tumors we interrogated the relationship between iKRas and S100A10." (PMID 27351226, 2016). "Thus, two different mechanisms are activated by S100A10 in pancreatic cancer, with the overall goal of accelerating tumor progression." (PMID 37892132, 2023). "Similarly, S100A10 was found to function in surface plasminogen activation, invasiveness, and the growth of pancreatic cancer cells." (PMID 36114176, 2022). "Multiple studies have found that S100A10 mRNA is upregulated in pancreatic tumours." (PMID 35204653, 2022). "Thus, we proposed that S100A10 upregulation by pancreatic tumors is a late event in pancreatic cancer progression." (PMID 34944416, 2021). "We then examined S100A10 protein expression in 89 pancreatic tumors using IHC." (PMID 34944416, 2021). "The protein expression data was consistent with mRNA data, which supports the hypothesis that S100A10 plays a role in pancreatic cancer." (PMID 34944416, 2021). "Additionally, in Pei’s datasets, S100A10/A11/A14/A16/P were found higher expressed in pancreatic carcinoma (fold change = 3.54, 4.95, 6.46, 4.40, 77.93) in comparison with normal samples." (PMID 34804125, 2021). "S100A10 levels are increased in patients with pancreatic cancer." (PMID 27351226, 2016). "These patient data highlight the potential importance of S100A10 in KRAS-driven pancreatic cancer." (PMID 27351226, 2016). "Interestingly, we also observed that activation of KRas in mouse pancreatic cancer cells resulted in the increased expression of S100A10." (PMID 27351226, 2016). "S100A10 could act in a paracrine or autocrine manner on pancreatic cancer cells." (PMID 37627239, 2023). "Apart from S100A10, ANXA2 has also been shown to co-localise with S100A6 on the plasma membrane of pancreatic cancer cells and tissue, and together, promoted increased tumour cell motility." (PMID 35204653, 2022). "To further investigate the S100A10 levels in clinically relevant cancer cell lines, we depleted KRAS from A549 (lung cancer) and MiaPaca2 (pancreatic cancer) cells and analysed S100A10 expression by western blotting." (PMID 27351226, 2016). "For instance, previous studies reported that S100A2 and S100A10 were the negative biomarker for pancreatic cancer (PC), while S100A4 was profoundly involved in the chemoresistance and survival in are negative prognostic biomarkers in PC cells." (PMID 37420211, 2023). "S100A10 protein is also overexpressed in pancreatic tumors compared to adjacent nonductal stroma and normal ducts." (PMID 30009399, 2018). "We demonstrated that S100A10 mRNA and protein are overexpressed in human pancreatic tumors compared to normal ducts and nonductal stroma." (PMID 30009399, 2018). "Moreover, overexpression of S100A6, S100A10, S100A11, S100A14, and S100A16 may impair the infiltration and cytolytic activity of cytotoxic lymphocytes in pancreatic cancer." (PMID 36982351, 2023). "S100A10 is upregulated in pancreatic cancer but low in nonductal stroma and normal tissue, regardless of whether it was adjacent to PanINs or PDAC." (PMID 34944416, 2021).
hepatocellular carcinoma (10 papers, 2013 to 2025). A malignant tumor that arises from hepatocytes. "S100A10 regulates apoptosis and viability of hepatocellular carcinoma cells probably associated with ANXA2/Akt/mTOR pathway." (PMID 37420211, 2023). "Most evidence of the regulation of S100A10 by miRNA and LncRNA has been obtained from studies in hepatocellular carcinoma (HCC) models." (PMID 37892132, 2023). "To further verify the biological functions of S100A10, we examined the expression levels of S100A10 mRNA and protein in hepatocytes (L02) and hepatoma cells (HepG2, Huh7, LM3, SNU449)." (PMID 37420211, 2023). "Overexpression of S100A10 reduced apoptosis of hepatocellular carcinoma cells, while silencing of S100A10 increased apoptosis of hepatocellular carcinoma cells." (PMID 37420211, 2023). "In hepatocellular carcinoma, S100A10 plays a pivotal role in tumor initiation, self-renewal capacity, chemoresistance, and metastasis, as validated in vivo and in experimental animal models." (PMID 37892132, 2023). "In summary, we basically concluded that S100A10 was involved in the growth process of hepatocellular carcinoma through the ANXA2/Akt/mTOR signaling pathway." (PMID 37420211, 2023). "In hepatocellular carcinoma, the over-expression of S100A10 accelerates cell proliferation in Hep3B and Huh-7 cells, while decreased S100A10 expression shows the opposite effect on the proliferation capacity of SK-Hep-1 and HepG2 cells." (PMID 36612197, 2022). "In hepatocellular carcinoma, LINC00174 was significantly up-regulated and promoted the malignant phenotype of hepatocellular carcinoma cells by regulating S100A10 as a sponge of miR-320." (PMID 34226413, 2021). "(2013) recently demonstrated that the miR‐590‐5P directly binds 3′ UTR of S100A10 to inhibit its expression which was concomitant with downregulation of CCND1 in HepG2 hepatocellular carcinoma cells." (PMID 30009399, 2018). "We have analyzed S100A10 expression in hepatocellular carcinoma and paraneoplastic tissues from clinical samples and the results show that S100A10 contents were increased in cancer tissues." (PMID 23598417, 2013). "In the present study, we found that the expression of a microRNA, miR-590-5P, was down-regulated and S100A10 was up-regulated in six hepatocellular carcinoma cell lines." (PMID 23598417, 2013). "Although poorly investigated in the context of liver diseases, another member of the S100 family, S100A10, has been shown to be one of the main proteins present at the surface of lipid droplets in the liver and to promote in vitro the growth of hepatoma cells lines." (PMID 40841353, 2025). "In hepatocellular carcinoma cells, S100A10 expression was lowest in HepG2 and highest in SNU449." (PMID 37420211, 2023). "Up to now, S100A10 has been reported to be up-regulated in several cancers, including lung cancer, gall bladder adenocarcinoma, colorectal adenocarcinoma, and hepatocellular carcinoma, which correlated with worse survival outcomes." (PMID 36612197, 2022). "We speculate that S100A10 and ANXA2 may also activate the Akt/mTOR pathway in hepatocellular carcinoma." (PMID 37420211, 2023).
renal cell carcinoma (10 papers, 2002 to 2024). "Early studies identified the oncogenic role of S100A10 in ovarian, gastric, breast, and renal cell cancers." (PMID 39117605, 2024). "AXL signaling increased renal cell carcinoma expression of the pro-angiogenic factor S100A10, and an AXL inhibitor combined with a VEGF inhibitor decreased the growth of patient-derived xenografts and vessel density in mice." (PMID 34884986, 2021). "Non-cancerous resections adjacent to kidney tumors show no expression of S100A10; however, S100A10 is expressed in renal cell carcinoma lesions." (PMID 30572596, 2018).
COVID-19 (9 papers, 2021 to 2025). A disease caused by infection with severe acute respiratory syndrome coronavirus 2. "A study comparing NK and NK-T cell subsets between COVID-19 patients and healthy individuals identified S100A10 as a marker for COVID-19-derived NK-T cells." (PMID 37892132, 2023). "More recently, S100A10 has been examined for its role in the inflammatory condition of COVID-19 patients." (PMID 37892132, 2023). "Another study looking at peripheral blood samples from COVID-19 cases observed an upregulation of S100A10, S100A4, and S100A9 mRNA." (PMID 37892132, 2023). "As in naive and memory B cells, S100 genes (such as S100A10) were more upregulated in in the p-PB groups, especially severe COVID-19." (PMID 37638019, 2023). "We also found an increased expression of CD63, ITGB2, CD37, CD2 and IL23R markers and the reduction in CXCR4, CD69, CD48, ICAM1 and S100A10 markers in COVID-19-derived NK-T cells compared to controls." (PMID 34944610, 2021). "Interestingly, TIMP-1 is the most related differential gene between RPS29 and S100A10, these results demonstrate the presence of intracranial inflammatory response in COVID-19 patients." (PMID 37063869, 2023). "According to some studies, S100A4, S100A9, and S100A10 expression is proportional to neutrophil/lymphocyte ratio, and may reduce peripheral blood lymphocytes in COVID-19 patients." (PMID 35892571, 2022). "In addition, a recent study demonstrated that S100A4, S100A9, and S100A10 have a role in the inflammatory conditions, as well as the severity, of COVID-19 patients, and have the ability to influence the prognosis of the severe form of the disease." (PMID 35892571, 2022). "RPS29, S100A10, and TIMP1 were the critical genes in the brain pathology of COVID-19 in elderly patients." (PMID 37063869, 2023). "Further WGCNA analysis suggested that ribosomal dysfunction may play a key role in brain dysfunction in elderly COVID-19 patients, with RPS29, S100A10, and TIMP1 as key molecules." (PMID 37063869, 2023).
glioblastoma (8 papers, 2008 to 2022). The most malignant astrocytic tumor (WHO grade IV). "Madureira’s group examined the hypoxic response in five glioblastoma cell lines and observed upregulation of S100A10 in four of five cell lines." (PMID 34944416, 2021). "In both grade I astrocytoma and glioblastoma (GBM) S100A10 had the highest tag count of 134 and 112.3, respectively." (PMID 18781180, 2008). "GEPIA analysis also showed that S100A10 was upregulated in glioblastoma when compared to non-cancerous brain samples." (PMID 34944416, 2021).